SLC7A11 (solute carrier family 7 member 11)
Diseases named in the same sentence as SLC7A11 in open-access papers (continued):
Sharing a sentence is not in itself a finding about the gene and the disease.
ischemic stroke (15 papers, 2022 to 2026). A stroke disorder caused by obstruction of blood flow to the brain, due to thrombotic (local blood clot formation) or embolic (due to a blood clot or other material traveling from another site) event. "One of the creative findings in the current study is that ischemic stroke‐mediated iron overload causes the opposite alterations in endogenous antioxidant defense systems, Nrf‐2‐mediated GPX4 and SLC7A11 expression in neurons and astrocytes." (PMID 41195589, 2026). "Although the expression of SLC7A11, were found to be upregulated by Eda-Dex, the mechanism of Eda-Dex in ferroptosis in ischemic stroke is still to be investigated." (PMID 40351418, 2025). "Single cell analysis shows that the seven types of DRGs (ACTB, IQGAP1, FLNA, PDLIM1, MYH10, INF2 and SLC7A11) are mainly distributed in the immune cell types of ischemic stroke." (PMID 40109666, 2025). "Exosomal circBBS2 inhibits ferroptosis by targeting miR-494 to activate SLC7A11 signaling in ischemic stroke." (PMID 40823304, 2025). "This indicates that SLC7A11/GSH/GPX4 was probably one of the targets for DL-NBP to cure ischemic stroke." (PMID 36909944, 2023). "Collectively, our findings identified a METTL3/AU020206/YTHDC2/SLC7A11 axis that curbs ferroptotic injury after cerebral I/R and highlight epitranscriptomic modulation of lncRNA stability as a promising therapeutic avenue for ischaemic stroke." (PMID 41154582, 2025). "Consistent with our findings, recent studies highlight that KAM activates Nrf2, thereby upregulating SLC7A11 and GPX4 to mitigate lipid peroxidation and iron overload in neuronal models of ischemic stroke." (PMID 41533024, 2026). "Therefore, SLC7A11, a subunit of the Xc system that imports cystine through the export of glutamate at a 1:1 ratio, may be involved in the crosstalk between ferroptosis and disulfidptosis in ischemic stroke." (PMID 40109666, 2025). "In the meanwhile, the downstream molecules of NRF2, such as HO-1, SLC7A11, and GPX4, by which Eda-Dex exserts anti-oxidative stress function, have been investigated is ischemic stroke." (PMID 40351418, 2025). "In this study, these levels of ROS, MDA, GSH, iron and several ferroptosis‐related key proteins, such as GPX4, SLC7A11 and ACSL4, were detected in mice possessing ischemic stroke." (PMID 39233353, 2024). "No study has evaluated how Dl-3-n-butylphthalide affects the ferroptosis SLC7A11/GSH/GPX4 signal pathway and blood–brain barrier (BBB) PDGFRβ/PI3K/Akt signal pathways in the rat middle cerebral artery occlusion/reperfusion (MCAO/R) model of ischemic stroke." (PMID 36909944, 2023).
esophageal cancer (14 papers, 2019 to 2025). A primary or metastatic malignant neoplasm involving the esophagus. "SLC7A11 gene expression was identified as a response prediction biomarker for APR-246 treatment in esophagus carcinoma cell lines, whereby low expression levels of the cysteine importer are associated with a higher response to APR-246 treatment." (PMID 34503286, 2021). "Low amounts of glutathione are completely bound by APR-246/MQ and the expression of SLC7A11 has been proposed as a predictive biomarker of APR-246 responsiveness in esophagus carcinoma cell lines." (PMID 34503286, 2021). "For esophageal cancer cells with a high level of SLC7A11, GSH can be synergistically depleted by the combined use of oridonin and γ-glutamyl cysteine synthetase inhibitor (BSO), leading to irresistible ROS accumulation and cell death." (PMID 32010620, 2019). "In esophageal cancer, a better marker for response to eprenetapopt (also in combination with chemotherapy) may be expression of SLC7A11 (solute carrier family 7, member 11), specific for cysteine/glutamate transport." (PMID 36831398, 2023). "CircPVT1 sponge miR-30a-5p targets and binds frizzled class receptor 3 (FZD3), affects the expression levels of p-β-catenin, GPX4 and SLC7A11, inhibits cellular ferroptosis, affects esophageal cancer 5-FU chemotherapy sensitivity and promotes the development of esophageal cancer." (PMID 37152286, 2023). "This study found that SLC7A11 is highly expressed in most cancers, such as COAD, LUAD, and esophageal cancer (ESCA)." (PMID 35517862, 2022).
Parkinson disease (14 papers, 2011 to 2025). A progressive degenerative disorder of the central nervous system characterized by loss of dopamine producing neurons in the substantia nigra and the presence of Lewy bodies in the substantia nigra and locus coeruleus. "Hypermethylation of cg06690548 has also recently been associated with downregulation of SLC7A11 in Parkinson’s disease." (PMID 37858220, 2023). "In brain, a recent study showed that cg06690548 hypermethylation in Parkinson’s disease was associated with downregulation of the SLC7A11 gene and reduced GSH levels and increased oxidative stress triggered degeneration of dopaminergic neurons in the substantia nigra." (PMID 34857913, 2022). "Strikingly, SLC7A11 overexpression (OE‐SLC7A11) significantly improved motor performance in diabetic rats with 6‐OHDA‐induced parkinsonism, as demonstrated by a battery of behavioral tests." (PMID 40613317, 2025). "Increased SLC7A11 protein expression was also discovered in the striatum in a Parkinson’s disease rat model." (PMID 34575878, 2021). "Moreover, iron deposition and its associated molecular mechanisms, including alterations in the expression of DJ-1 and SLC7A11 genes, as well as the production of lipid peroxides, are closely related to ferroptosis in Parkinson’s disease." (PMID 39830208, 2024). "Interestingly, Slc7a11 KO mice are protected from neurotoxic insults induced by 6-hydroxydopamine (6-OHDA), which can trigger Parkinson’s Disease (PD) via decreasing extracellular glutamate levels in the brain." (PMID 31936571, 2020).
acute kidney injury (13 papers, 2021 to 2025). Sudden and sustained deterioration of the kidney function characterized by decreased glomerular filtration rate, increased serum creatinine or oliguria. "In another study, quercetin was found to increase the levels of SLC7A11 and GPX4 expression and subsequently enhance cell viability, by inhibiting ATF3, thereby reducing the risk of acute kidney injury (AKI)." (PMID 39171207, 2024). "Another recent publication reported that MT attenuated acute kidney injury by inhibiting ferroptosis through its effects on the nuclear factor erythroid 2–related factor 2 (Nrf2)/solute carrier family 7 member 11 (Slc7a11) axis." (PMID 37371903, 2023). "Quercetin (QCT) significantly inhibits SLC7A11 and GPX4 expression and ameliorates macrophage chemotaxis in acute kidney injury." (PMID 39687171, 2024). "It was shown that ruscogenin could increase the levels of Slc7a11 and HO-1 by suppressing Rev-erbα/β, thereby inhibiting the occurrence of folic acid-induced iron death in kidney tissue cells and preventing the development of acute kidney injury under pathological conditions." (PMID 35845882, 2022).
acute myeloid leukemia (13 papers, 2021 to 2026). Acute myeloid leukemia (AML) is a group of neoplasms arising from precursor cells committed to the myeloid cell-line differentiation. "In acute myeloid leukemia patients, high expression of SLC7A11 is associated with poor prognosis." (PMID 37296281, 2023). "LINC00618 attenuates the expression of lymphoid-specific helicase (LSH), and LSH can increase the transcription of SLC7A11 after recruitment to the promoter regions of SLC7A11, further promoting ferroptosis in human acute myeloid leukemia (AML)." (PMID 37065473, 2023). "It inhibits ferroptosis in TSCC cells by inhibiting miR-125b-5p and enhancing SLC7A11, while in acute myeloid leukemia (AML), muscle ARNT-Like protein-1 (Bmal1) prevented RSL3-induced ferroptosis through EZH2-mediated EBF3 methylation to inhibit the expression of EBF3 and ALOX15." (PMID 39518098, 2024). "And high expression of SLC7A11, GPX4, and AIFM2 were significantly correlated with the shortened OS of acute myeloid leukemia (LAML) patients." (PMID 34722530, 2021). "And high expression of SLC7A11, GPX4, and AIFM2 were significantly correlated with the shortened OS of acute myeloid leukemia patients." (PMID 34722530, 2021). "Additionally, HNK induced the ferroptosis of acute myeloid leukemia (AML) in a non-canonical manner by significantly upregulating HO-1 expression instead of downregulating SLC7A11 expression." (PMID 39021832, 2024). "In this study, we identified SE-associated genes by integrating cell-specific SEs with RNA-seq data and found six genes (CAPG, CD207, GPR132, SLC7A11, HIPK3 and FCER1G) that are correlated with poor prognosis in acute myeloid leukemia (AML) patients according to the TCGA-LAML database." (PMID 37296281, 2023).
colitis (13 papers, 2023 to 2026). Inflammation of the colon. "In vivo, inhibition of the METTL1/m7G/SLC7A11 axis exacerbates chronic DSS-induced colitis but alleviates acute DSS-induced colitis, revealing a switch from adaptive to maladaptive signaling with escalating metabolic stress." (PMID 42212324, 2026). "To elucidate the mechanism by which FXR regulates ferroptosis in colitis, we performed RNA sequencing and then focused on the subunit of System Xc, termed SLC7A11." (PMID 40681992, 2025). "This study highlights that FXR exerts therapeutic effects against colitis by antagonizing ferroptosis via transactivation of SLC7A11 and increasing GPX4 stability." (PMID 40681992, 2025). "The results revealed that DSS challenge impaired SLC7A11 in DSS-induced colitis, whereas Fex treatment significantly elevated SLC7A11 levels." (PMID 40681992, 2025). "We utilized wild-type and SLC7A11−/+ mice to assess the inflammatory damage in DSS-induced colitis in vivo." (PMID 40360947, 2025). "This study investigates the effect and underlying mechanism of targeting SLC7A11 in mitigating dextran sulfate sodium (DSS)-induced intestinal inflammation and injury in colitis." (PMID 40360947, 2025). "Taken together, these data verified that PD ameliorates DSS-induced colitis by inhibiting ferroptosis activation via an Nrf2/Slc7a11/Gpx4-dependent signaling pathway." (PMID 39877390, 2024). "Erastin, an inhibitor of Slc7a11, exacerbated ROS levels and mitochondrial iron accumulation during colitis while negating the protective effects conferred by PD in vitro." (PMID 39877390, 2024). "We then analyzed the composition of the intestinal microbiota, which can also regulate the development of colitis, in naïve WT, Cth–/– and Slc7a11–/– mice." (PMID 39427081, 2024). "We uncovered the inhibition of the SLC7A11/GSH/GPX4 antioxidant system in the colitis rats, of which the activity was enhanced by XJS treatment." (PMID 37153794, 2023). "One study suggested that inhibiting the activation of the miR-144-3p/SLC7A11 signaling pathway could alleviate DSS-induced colitis in mice." (PMID 40478904, 2025). "In vivo inhibition of SLC7A11 markedly alleviated DSS-induced colitis symptoms." (PMID 40360947, 2025). "Interestingly, IHC staining results revealed that, except for TXNRD1, the expression levels of ACSL4 and LPCAT3 in colitis mice were higher than those in the normal control group, while SLC7A11 and GPX4 displayed the opposite consequence." (PMID 40691131, 2025). "The different modes and mechanisms of SLC7A11 involved in the regulation of disulfidptosis may exist in the intestinal mucosa of patients with UC versus those of DSS-induced colitis mice and should be further explored." (PMID 38977802, 2024). "We also examined whether the colitis-protective mechanism of PD is mediated by ferroptosis through the Nrf2/Slc7a11/Gpx4 axis in vivo." (PMID 39877390, 2024). "We further tested the mRNA and protein levels of the characterized genes in the intestinal mucosa of DSS-induced colitis mice and UC patients, and the results showed that the mRNA and protein levels of SLC7A11, NDUFS1, LRPPRC, and CD2AP were dramatically downregulated in DSS-induced colitis mice." (PMID 38977802, 2024). "The prevention of colitis by PD might be related to ferroptosis and the upregulation of Slc7a11 expression." (PMID 39877390, 2024). "Upregulation of SLC7A11 to inhibit ferroptosis may be an effective approach for amelioration of colitis." (PMID 37153794, 2023). "However, the profile and precise regulatory mechanism of SLC7A11 in colitis are still obscure." (PMID 40681992, 2025). "In conclusion, FXR is compromised in colitis, and restoring FXR has a protective effect on colitis by suppressing ferroptosis via direct transactivation of SLC7A11 and stabilizing GPX4." (PMID 40681992, 2025).
colitis (continued). "Similarly, DSS-induced colitis suppressed the expression of key ferroptosis-regulating proteins such as GPX4, SLC7A11, and SLC3A2, while elevating HO-1 levels as a compensatory response to oxidative stress." (PMID 39940407, 2025). "This does not appear to occur through the regulation of the mucosal concentration of cysteine, since mice lacking the cystine transporter SLC7A11 were not protected from colitis." (PMID 39427081, 2024). "Mechanistically, we determined that the deletion of the gene Slc7a11 encoding for solute carrier family 7 member 11, the transporter of the anionic form of cysteine, does not affect DSS colitis." (PMID 39427081, 2024). "We also recognize a limitation that the mechanisms of NF-κB and STAT3 on regulating the SLC7A11/GSH/GPX4 antioxidant axis and XJS targeting FGL1 to inhibit colitis are not verified in vitro, which will be conducted in a future study." (PMID 37153794, 2023).
oral squamous cell carcinoma (13 papers, 2017 to 2025). "Excessive ROS production and enhanced death via the upregulation of xCT (SLC7A11), an antiporter of cystine and glutamate, was observed in breast, gastric, and oral squamous cell carcinoma cells treated with salubrinal under conditions of glucose deprivation." (PMID 40650182, 2025). "Knocking down circ_0000140 enhances the sensitivity of oral squamous cell carcinoma cell lines to cisplatin by modulating the miR-527/SLC7A11 signaling pathway, leading to increased ferroptosis." (PMID 38994627, 2024). "Previous data demonstrated that silencing of circFNDC3B limited GPX4 expression and enhanced ROS, total iron level, and Fe2+ in oral squamous cell carcinoma cells via the miR-520d-5p/SLC7A11 axis." (PMID 35847582, 2022). "MiR-375 is downregulated in oral squamous cell carcinoma, and treatment with miR-375 mimics reduced SLC7A11 levels and acted as a tumor suppressor." (PMID 35755805, 2022). "We aimed to detect the functions of miR‐375/SLC7A11 axis on oral squamous cell carcinoma (OSCC) cell proliferation and invasion." (PMID 28627030, 2017). "Additionally, the previous study has shown that the miR-375/SLC7A11 axis suppresses oral squamous cell carcinoma proliferation and invasion; this is consistent with our work." (PMID 34090492, 2021).
cholangiocarcinoma (12 papers, 2023 to 2025). A carcinoma that arises from the intrahepatic biliary tree (intrahepatic cholangiocarcinoma) or from the junction, or adjacent to the junction, of the right and left hepatic ducts (hilar cholangiocarcinoma). "Inhibiting ferroptosis by regulating the phosphatase and tensin homolog/solute carrier family 7 member 11/glutathione peroxidase 4 axis, thereby promoting cholangiocarcinoma (CCA) proliferation and migration." (PMID 39314046, 2024).
injury (12 papers, 2021 to 2026). Damage inflicted on the body as the direct or indirect result of an external force, with or without disruption of structural continuity. "Ferroptosis has been reported to be involved in many pathological processes including cancer development, traumatic brain injury, and coronary artery disease, and SLC7A11 is a critical key factor in the processing of ferroptosis." (PMID 36831172, 2023). "In intestinal I/R, Nrf2 plays a protective role as it can regulate SLCA11 and HO-1 to limit ferroptosis to attenuate secondary acute lung injury, and can modulate TERT and SLC7A11 to weaken secondary acute liver injury." (PMID 36052333, 2022). "Moreover, our study also showed that YAP1 promoted the expression of SLC7A11 and increased the GPX4 and GSH level both in septic liver injury mice and LPS-stimulated LO2 cells, while suppressed the expression of ACSL4." (PMID 36182901, 2022).
brain tumors (11 papers, 2014 to 2025). "The glutamate exchanger xCT (SLC7a11) is causally linked with the malignancy grade of brain tumors and represents a key player in glutamate, cystine and glutathione metabolism." (PMID 27612422, 2016). "illustrated that ATF4 prompted tumour proliferation, angiogenesis and malignancy of primary brain tumours via xCT/SLC7A11, a crucial regulator gene of the ferroptosis." (PMID 38652216, 2024). "In many neurological conditions, such as inflammation/degenerative diseases, hypoxic diseases, epilepsy and brain tumors, the transcription of the Slc7a11 gene is increased." (PMID 25339860, 2014). "In addition, ATF4 in malignancy of primary brain tumours increases tumour angiogenesis and shapes vascular architecture in an SLC7A11-dependent manner." (PMID 35804831, 2022). "Unlike primary brain tumours, SLC7A11 reduces choroidal neovascularisation in age-related macular degeneration by inhibiting ferroptosis and vascular endothelial growth factor (VEGF) production." (PMID 35804831, 2022).